MICC (MHC class I polypeptide-related sequence C (pseudogene))
Synonyms: PERB11.3
Gene: Unprocessed pseudogene on chromosome 6 (30,414,715 to 30,419,319, forward strand). Ensembl gene ENSG00000226577.
Diseases named in the same sentence as MICC in open-access papers:
MICC is named in the same sentence as 1 disease in open-access papers, as found by Europe PMC text mining. Sharing a sentence is not in itself a finding about the gene and the disease. The quoted sentences say what the papers report.
infection (2 papers, 2025). The state of being infected such as from the introduction of a foreign agent such as serum, vaccine, antigenic substance or organism. "Deletion mutants of MicC were more competitive in the small intestines of BALB/c mice compared to wild-type strains, indicating that MicC inhibits bacterial virulence during infection." (PMID 40444151, 2025). "Coordinating SPI1 regulation and downregulation of OmpD by InvR and MicC might lessen any stress in outer membrane assembly during infection." (PMID 40013798, 2025).